CD4 (CD4 molecule)
Diseases named in the same sentence as CD4 in open-access papers (continued):
Sharing a sentence is not in itself a finding about the gene and the disease.
tumor (continued). "The PI4K IIIα inhibitor radiosensitized tumor cells by modulating PI3Kδ and regulated the immune response by regulating PD-L1 expression and affecting the CD4(+)/CD8(+) ratio of T lymphocyte." (PMID 29299156, 2017). "In all patients, an increase in CD4 + T-cell population in both tumor tissue and peripheral blood was found, probably positively related to clinical benefit." (PMID 28680882, 2017). "On the other hand, only about 20% of TCRs found on dominant 35 CD4+Teff clones in tumor infiltrates were also found among circulating lymphocytes of control, non-tumor-bearing mice albeit at different frequency." (PMID 28638937, 2017). "By applying high-throughput DNA sequencing, we were able to identify TCRs of tumor-reactive CD4+Teffs and Tregs." (PMID 28638937, 2017). "In co-culture cytotoxicity assays, target tumor cells were identified by the CD4+, CD56- immunophenotype (labeled in blue on flow cytometry charts)." (PMID 29348865, 2017). "Here we provide direct evidence that administration of recombinant IL-7 can potentiate the expansion, maintenance and function of adoptively transferred tumor-reactive CD4+ T cells." (PMID 28939858, 2017). "In vivo study demonstrated that Cu- and Zn-AMSs markedly induced anti-tumor-immunity and enhanced CD4+ and CD8+ T cell populations in splenocytes of mice." (PMID 29196724, 2017). "To study the potential effect of these differences on our predictions, we established reference gene expression profiles of each major tumor-infiltrating immune cell type (i.e., CD4 T, CD8 T, B, NK, macrophages)." (PMID 29130882, 2017). "In nonsmokers and young patients, increased percentages of naïve CD4+ T cells and decreased memory CD4+ T cells were observed, which were consistent with tumor characteristics of these patients." (PMID 29137371, 2017). "The A2AAR receptor is linked to the immune response of tumours by T regulatory cell function, suppression and modulation of natural killer cell cytotoxicity, and tumour-specific CD4+/CD8+ activity." (PMID 29258235, 2017). "Nevertheless, it is believed widely that tumour‐specific CD4+ T cells also play a vital role in anti‐cancer immunity." (PMID 27324616, 2017). "Many human cancers are characterized by tumor-infiltrating lymphocytes that include CD4 and CD8 T cells, indicating that tumors do evoke an immune response, probably due to the numerous mutant proteins expressed in cancerous cells." (PMID 28646041, 2017). "Naive CD4+ T cells adhere to tumor slices in proportion to the abundance of CCL18-producing macrophages." (PMID 28290464, 2017). "In fact, CD39+ cells have been found to be highly represented in both CD4+ and CD8+ subpopulations in tumor tissues and were linked to immunosuppressive functions." (PMID 28264447, 2017). "CD4+ T cells have traditionally been regarded as helpers to achieve full activation of tumor-specific cytotoxic T lymphocytes (CTLs)." (PMID 29250133, 2017). "Although tumor antigen-stimulated CD4+ T cells can produce IFN-γ (Th1) or IL-4 (Th2) and both these cytokines can recruit other tumoricidal cells to the tumor site, tumor rejection is mediated by IL-4." (PMID 29250133, 2017). "Our study also found that the amount of CD4+CD25+Foxp3+ regulatory T cells in tumor tissue was significantly decreased in SBE treated group." (PMID 28086772, 2017). "To examine the role of Th17 and Treg cell plasticity in tumour progression, we induced Th17/Treg cell differentiation in vitro by culturing CD4+ T cells from Foxp3GFP mice under Th17–Treg-driving conditions." (PMID 28290453, 2017). "LAG-3 is highly co-expressed with other immune inhibitory molecules, including TIM-3, PD-1, 2B4 and T-cell immunoglobulin and ITIM domain (TIGIT), on tumor-specific CD4+ effector T cells." (PMID 28404974, 2017). "Regarding tumor-specific immune responses, tumor antigen-loaded DCs plus lenalidomide showed significantly increased percentages of NK cells, CD4+ T cells and CD8+ T cells compared with the other groups." (PMID 28460478, 2017).
tumor (continued). "RKO cells were found to induce the greatest expression levels of FOXP3 in naïve CD4 T cells, and blockade of TGFβ abrogated this effect, confirming the importance of this cytokine for tumour-mediated Treg induction in humans." (PMID 28239749, 2017). "In the current study, DCs were stimulated with agonistic anti-CD40 mAbs after tumor-antigen loading and were inoculated s.c. into mice that were irradiated and reconstituted with ex vivo—expanded CD4+ T cells." (PMID 28854279, 2017). "High‐dose IL‐2 is approved in cancer therapy, where it promotes tumour killing by activating NK cells and CD4+ and CD8+ effector T cells 12; however, pulmonary vascular leakage occurs as a side effect to this treatment." (PMID 28176332, 2017). "This study showed rNDV-TV induced an antitumor T cell response to WEHI164 cells, and major subsets of cells involved in tumor exclusion were CD4+ and CD8+ cells, together with NKT cells." (PMID 28864944, 2017). "Some studies have shown a protective role in hepatocarcinogenesis through suppression of growth of established tumors, while certain B cell populations impair CD4+ T cell activation and thus promote tumor progression." (PMID 28915576, 2017). "Ibrutinib inhibits Th2-polarized CD4 T cells, thus skewing T cells toward a Th1 anti-tumor immune response." (PMID 29046826, 2017). "Although preliminary, these results support the fundamental contribution of CD4+ T cells in the recognition and killing of tumor cells and their potential boosting induced by SBRT." (PMID 29163540, 2017). "Meanwhile, A2AR blockade significantly reduced the population of CD4+ Foxp3+ Tregs and enhanced the anti-tumor response of CD8+ T cells." (PMID 28592285, 2017). "Surprisingly, depletion of CD4+ cells caused a slight, albeit non‐significant increase in tumor incidence in wt/HPV8 mice, indicating that CD4+ T cells are rather tumor‐suppressive in the HPV8 model under our experimental conditions." (PMID 27932444, 2017). "In the murine cancer model, targeting of IL-17A inhibited PDL1 expression in the tumor microenvironment, decreased the percentage of Treg cells in tumor-infiltrating lymphocytes, and promoted CD4+ and CD8+ T cells to secrete interferon gamma." (PMID 27935862, 2017). "Inhibin-α vaccination inhibited TSC tumor growth in both SJL/J and BALB/c mice and the effectiveness was associated with tumor infiltrates of activated CD4+ T cells." (PMID 28428886, 2017). "Together, these results suggest that Tregs are generated from naive CD4+ T cells responding via PITPNM3 to CCL18 produced in the tumor." (PMID 28290464, 2017). "CD4+ T cells can directly kill MHC class II positive tumor cells in a perforin/granzyme B cell-dependent manner and can indirectly eliminate tumor cells that lack expression of MHC class II by cytokine-mediated activation of macrophages." (PMID 28428886, 2017). "For high antigenicity of the tumor, a globally closed curve exists when the dosage of CD4+ T cells is small." (PMID 29250133, 2017). "Tumors display tumor-associated antigens on class I and class II HLA molecules at the cell surface, and these antigens can be recognized by CD8 and CD4 T cells." (PMID 28670312, 2017). "Tumor-infiltrating CD4+, CD8+ T and NKT cells increased after MART1 plasmid + AdMGshT, instead, tumor-infiltrating CD4+CD25+FoxP3+ regulatory T cells were decreased." (PMID 28178658, 2017). "In the tumor-draining regional lymph node cells, many proliferative CD4+CD25+ Treg cells inhibit the proliferation of effector cells within the same lymph node." (PMID 28796055, 2017). "Several obstacles preclude easy exploitation of natural tumour‐specific HLA‐II‐restricted CD4+ T cells." (PMID 27324616, 2017). "Taken together, these data suggest a requirement for CD4 ‘help’ in the generation of an effective CD8 anti‐tumor immunity." (PMID 28250921, 2017). "117Dual treatment led to a significant survival benefit in treated mice, and corresponded with an increase in tumour infiltrating CD4+ and CD8+ T cells." (PMID 29208938, 2017).
tumor (continued). "Allelic loss of MHC molecules prevents recognition of the tumor cells by CD8 T cells and, in some cases, even CD4 T cells." (PMID 29312332, 2017). "On the other hand, the tumor of 4T1.2/HER2 tumor-bearing mice had dramatically increased levels of CD3+/CD4+ and CD3+/CD8+ T cells than that of CT26/HER2 tumor-bearing mice." (PMID 28460461, 2017). "We also noticed a significant increase in the percentage of CD25+Foxp3+ cells in CD4+ T cells after tumor resection." (PMID 28178645, 2017). "At the same time, CD4+ T cells, which formed the larger fraction of the tumour-infiltrating T cell population, remained unaffected by genotype." (PMID 28924177, 2017). "By contrast, the frequency of tumor-infiltrating CD4+Foxp3+Tregs with the same TCR specificities as Teffs dropped by over 50% upon the DTA-1 treatment, but the unexpected diversity of their TCRs increased at the levels of amino acid and nucleotide sequences." (PMID 28638937, 2017). "As a result, infiltration of CD8+ T cells, CD4+ T cells, NK cells, and NK T cells in tumor tissues increased, after infection of oncolytic Ad-GMCSF-shTGFβ2, compared to the infection of oncolytic control adenovirus, but not significantly." (PMID 28178658, 2017). "Similar frequency of tumor-infiltrating ICOS+ CD4+ and ICOS+ CD8+ T cells was recovered from wt and Cbx3/HP1γ-insufficient mice." (PMID 28220815, 2017). "By contrast, cytotoxic CD4+ or CD8+ T cells recognize tumor-specific antigen and tumor-associated antigen and exert direct cytotoxic actions against tumor cells." (PMID 29221113, 2017). "To further investigate mechanism of anti-tumor immune response, we analyzed CD4+ and CD8+ T lymphocyte population and production of INF-γ and IL-2 in spleen." (PMID 29196724, 2017). "Increasing evidence has demonstrated that the adoptive transfer of tumor-specific CD4+ T cells can exert a stronger antitumor effect than CD8+ T cells in cancer therapy." (PMID 29250133, 2017). "For further confirmation, CD4+ T cells and CD11b+F4/80+Gr-1- macrophages were purified from tumor tissues, and analyzed for the mRNA expression of IL-25." (PMID 27909985, 2017). "Type-2 bias exists in T cells from mRCC patients, as tumor-specific CD4+ T cells displaying a T-helper type-2 bias have been isolated from mRCC patients." (PMID 28409322, 2017). "Treg cells were identified as subsets of CD4 + T cells, which play important roles in the regulation of immune tolerance, immunosuppression, development of inflammation and tumour." (PMID 28481908, 2017). "The elimination of CD4+ FOXP3+ Treg cells by T cells expressing the chimeric Klrk1/NKG2D receptor in the ovarian tumor microenvironment inhibited tumor growth and increased survival in mice." (PMID 28220815, 2017). "Tumor microenvironment contains the infiltration of tumor-promoting immunosuppressive cells such as TAMs, CD4+CD25+FOXP3+ Tregs, and MDSCs, which are necessary for tumorigenesis." (PMID 28143527, 2017). "In both patients, HF10 replicated well and induced tumor cell death with significant CD4+ or CD8+ cell infiltration." (PMID 28770166, 2017). "Functional analysis of CD4+ T cells has recognized CD25+FOXP3+CD4+ Tregs cells which have been found to suppress the tumor specific immune response." (PMID 28515351, 2017). "PBT anti-tumor activity was accompanied by an increase in activated CD8+ T-cells and a decrease in immunosuppressive tumor infiltrating cells including Gr-1+CD11b+ myeloid derived suppressor cells (MDSCs), CD4+CD25+ Tregs, and CD206+F4/80+ M2 macrophages." (PMID 29137411, 2017). "Mounting evidence indicates that CD4+ T cells can mediate tumor destruction through multiple mechanisms." (PMID 28939858, 2017). "Responsiveness to AIT correlates to the ability of culture-expanded TIL to produce interferon- γ (IFNγ) upon tumor reexposure, as well as to the dual presence of CD4+ and CD8+ T-cells in the administered AIT product." (PMID 27974697, 2017).
tumor (continued). "Recent evidence has also demonstrated that the transfer of CD4+ effector T cells augments antitumor immunity and inhibits tumor progression." (PMID 28854279, 2017). "Strikingly, efficacious tumour immunosurveillance due to tumour-specific CD4 + T cells was consistently related to increased local concentrations of both proinflammatory (IL-6, IL-1α, and IL-1β) and Th1-associated cytokines (IL-2, IL-12, and IFN-γ)." (PMID 29089667, 2017). "We previously showed that Listeria-based vaccine immunotherapy significantly reduces Treg/CD4+ cell ratio in the tumor microenvironment." (PMID 28807056, 2017). "The inhibition of tumor growth was accompanied by increased ratio of TILs to B16-Ep63K tumor cells, but the proportion of Tregs among TILs and lymph node T cells decreased, while the proportion of CD4+Teffs increased." (PMID 28638937, 2017). "While CD4+ T cells are known to infiltrate the GBM tumor microenvironment and a significant proportion express PD-1, little is known about their influence on an immune response." (PMID 28880903, 2017). "To this end, we injected IL-2 neutralizing monoclonal antibodies to tumor-bearing mice that received adoptive transfer of tumor-specific CD4+ T cells following CTX preconditioning." (PMID 28939858, 2017). "Treatment with anti‐TIM3 monoclonal antibody effectively suppressed tumor growth through restoring effector T‐cell function by targeting CD4+TIM3+ cells and CD8+TIM3+ cells and decreasing MDSCs." (PMID 28102051, 2017). "This study suggested that the IL-4 produced by CD4+ cells upon a chronic activation, promotes the polarization and pro-tumor bioactivity in macrophages, that in turn enhance tumor cells malignancy and metastasis." (PMID 28927416, 2017). "Analysis of lymphocytes isolated from both NDV-injected and distant tumours confirmed the upregulation of ICOS on both CD4+FoxP3− and CD8+ cells." (PMID 28194010, 2017). "To confirm the clinical significance of TI naive CD4+ T cells, we stained tumor sections for another naive T cell marker, CD62L18." (PMID 28290464, 2017). "The ratios of tumor-infiltrating CD4+ to FoxP3+ and CD8+ to FoxP3+ were significantly higher in the control group compared to the splenectomy group (8.2 ± 9.3 vs. 2.4 ± 1.5, p=0.046; 2.5 ± 1.4 vs. 1.5 ± 0.4, p=0.031, respectively)." (PMID 29179479, 2017). "Only seen in ER- cell lines, PD-L1 up-regulation was associated with increased HLA-DR tumor cells expression, CD4+ Foxp3+ CTLA-4high Treg down-regulation in vitro, increased T cells tumor infiltration, longer survival and tumor growth inhibition in vivo." (PMID 29371976, 2017). "The anti-tumor effect of PBT was lost in mice where CD4+ and CD8+ T cells were antibody depleted, implying that PBT stimulates an anti-tumor immune effect that is T-cell dependent." (PMID 29137411, 2017). "In the present study, elevated A2AR was detected on the surface of CD4+ Foxp3+ Tregs in 2cKO tumor bearing mice, emphasizing the potential role of A2AR signaling in regulating the expansion or functions of Tregs in HNSCC." (PMID 28592285, 2017). "HLA class I- and class II-restricted CD8+ and CD4+ T-cell responses are essential for the immune system to mount a successful anti-tumor immune defense or to remove infected." (PMID 28264017, 2017). "In a mixed tumor-leukocyte reaction, tumor cells infected with EnAd gave a strong activation of dendritic cells that led in turn to potent activation of CD4 T cells." (PMID 28345021, 2017). "Though PD-L1 blocking increased CD8+T cell frequency and CD8+T to CD4+T cells ratio in this human PD-L1 tumor model, we need take tumor volume in consideration." (PMID 28202921, 2017). "In contrast, both CD4+ and CD8+ T cell responses as well as T cell-mediated protection against tumor growth were comparable for linked and mixed antigen formulations." (PMID 28321220, 2017).
tumor (continued). "The majority of long-lived tumor-specific CD4+ T cells originated from ex vivo—expanded donor cells, whereas tumor-specific CD8+ T cells were primed from irradiated recipient cells." (PMID 28854279, 2017). "Tumor-infiltrating PD-1—CD4+ effectors also expressed many unique gene sets, including those related to metabolism." (PMID 28880903, 2017). "Activated CD4+ cells can also exert cytotoxic-independent anti-tumor activities, by recruiting other effector cells such as macrophages and eosinophils or by direct lysis of MHC class II-positive T cells." (PMID 28977830, 2017). "NRP1 was also detected on tumor-infiltrating CD4+ and CD8+ T cells isolated from patients undergoing resection for metastatic melanoma and correlated with antigen experienced CD45RO phenotype." (PMID 29067024, 2017). "We found that perivascular Foxp3+, and CD4+ T cells in the primary tumors correlated with tumor blood vessels." (PMID 29163521, 2017). "CD4+ CD25high CD127low regulatory T-cells (Tregs), PD-1+, Tim-3+, and PD-1+ Tim-3+ cells were up-regulated on tumor infiltrating T-cells from patients with GC compared to their expressions on corresponding peripheral blood and peritumoral T-cells." (PMID 29213216, 2017). "NRTUA treatment of tumor-bearing mice at tumor sites rapidly increased the production of TH1 cytokines interleukin 12 (IL-12) and IFN-γ and activated tumor-associated and splenic CD8+ and CD4+ T cells." (PMID 28910406, 2017). "Th17 cells, as a CD4+IL-17-producing subset of tumor-infiltrating lymphocytes (TILs), are found in the tumor microenvironment, including nasopharyngeal carcinoma, colon cancer, pancreatic cancer and ovarian cancer." (PMID 28537908, 2017). "Patients with the CD4 T cellshi subsets in the tumor have much better overall survival than those with the CD4 T cellslo subset." (PMID 29163537, 2017). "This activation of the autophagic pathway or cross-talk has been shown to cause an upregulation of HLA class II proteins which enhanced tumor Ag presentation to CD4+ T cells." (PMID 29399381, 2017). "Of note, MSCs induced greater infiltration of immune and immune-regulatory cells near tumor: CD4+ cells, CD11b+ cells, CD4+Foxp3+ regulatory T cells and CD11b+Ly6C+Ly6G− myeloid-derived suppressor cells." (PMID 29029511, 2017). "To analyze how DTA-1 treatment influences the clonal diversity of CD4+Teffs and Tregs in tumor-bearing TCRmini mice, we first compared the frequencies of 35 most frequent clones in pLN, dLN, and tumor from untreated and DTA-1 treated mice." (PMID 28638937, 2017). "Many studies have been reported the association of tumor infiltrating CD8(+) lymphocytes with prognosis and prognostic value of CD4(+)/CD8(+) ratio of tumor infiltrating lymphocytes." (PMID 29299156, 2017). "Tumor-infiltrating CD4+ and CD25+ cells were also present, but importantly, FoxP3+ Treg cells were only a minor subfraction of the tumor immune cell infiltrate." (PMID 29244745, 2017). "We previously established a CD4+ T cell-based ACT model system in which tumor-bearing mice receive CTX pre-conditioning followed by infusion of tumor-specific CD4+ T cells." (PMID 29340102, 2017). "But it is well documented that PD-L1 is also expressed by tumor cells and can inhibit the antitumor activity of CD4+ and CD8+ T cells via the inhibitory receptor PD-1." (PMID 28881675, 2017). "More importantly, the ratio of Treg cells in the CD4+ T cell population was lower in tumor tissues treated with RdB/IL12/DCN than in tissues treated with RdB/IL12 (P < 0.05) or RdB/DCN (P < 0.01)." (PMID 28002796, 2017). "Simeprevir showed significant radiosensitizing effect and immune modulatory function by affecting the CD4(+)/CD8(+) ratio of tumor infiltrating lymphocytes." (PMID 29299156, 2017). "Our data show that, in general, HLA‐I‐redirected CD4+ T cells required a TCR with an affinity higher than that needed by CD8+ T cells for optimal anti‐tumour effector function." (PMID 27324616, 2017).